RNU6-874P (RNA, U6 small nuclear 874, pseudogene)
Gene: Small nuclear RNA gene on chromosome 11 (129,202,966 to 129,203,070, forward strand). Ensembl gene ENSG00000199260.
Homologues: Orthologues: chimpanzee U6 (99% identical), macaque U6 (87% identical), guinea pig U6 (69% identical), guinea pig U6 (68% identical). Paralogues in human: RNU6-38P (78% identical), RNU6-1122P (77% identical), RNU6-14P (77% identical), RNU6-16P (77% identical), RNU6-25P (77% identical), RNU6-29P (77% identical), RNU6-33P (77% identical), RNU6-379P (77% identical), RNU6-476P (77% identical), RNU6-790P (77% identical), RNU6-1 (76% identical), RNU6-1011P (76% identical), and 1288 more.